EPCAM (epithelial cell adhesion molecule)
Diseases named in the same sentence as EPCAM in open-access papers (continued):
Sharing a sentence is not in itself a finding about the gene and the disease.
tumor (continued). "Thus, as shown in the profiling data, the pattern of CD117 and EpCam abundance on primary tumor EVs corresponds to the profile of MES-OV cells and extracellular vesicles." (PMID 36875773, 2023). "Consequently, our results suggest, that the EpCAM high-expressing and the EpCAM low-expressing CTC fractions originated from similar tumour cell clones." (PMID 36823365, 2023). "When evaluating EpCAM-based enrichment technologies for circulating tumour cells (CTCs), the cell lines used should closely resemble real CTCs, meaning the EpCAM expression of CTCs needs to be known, but also the EpCAM expression of cell lines at different institutions and times is important." (PMID 37055551, 2023). "Moreover, AsiC mixtures can be easily created from the assembly of individual AsiCs, and the combination of the four most effective EpCAM-AsiCs (targeting Upf2, Parp1, Cd47, and Mcl1) exerted a better tumor inhibition effect than the individual EpCAM-AsiCs." (PMID 36969696, 2023). "Tumor-specific mutations have not been reported in EpCAM so far, while hyperglycosylation of EpCAM at N74, N111, and N198 in carcinoma was commonly seen compared to normal epithelia." (PMID 37834237, 2023). "In two-dimensional tumor cell cultures, complete degradation of Ras proteins after 24 h was observed with EpCAM-targeted Ras degraders fused to ETA or DT in EpCAM-overexpressing MCF7 and HCT116 cells, with median inhibition concentration values at sub-nanomolar levels." (PMID 37485031, 2023). "Taken together, bsAb CD73xEpCAM may be useful to devise an alternate and more tumor-selective immunotherapeutic approach to overcome the CD73-mediated immunosuppression in patients with EpCAM-overexpressing refractory OC." (PMID 37509310, 2023). "Our findings here suggest that dysregulated mutant EpCAM expression may also generate stem cell phenotypes, since tumor-initiating cells are enriched with EpCAM." (PMID 37192201, 2023). "Additionally, tumor-associated macrophage (TAM), the metastasis stimulator, is capable of secreting TGFβ to impair EpCAM expression probably through SNAI2." (PMID 36077658, 2022). "Also, the progenitor/stemness markers SOX9, CD44v6, CD133, and EPCAM were highest in the tumor lesions." (PMID 35655220, 2022). "Later work demonstrated that the combination of surface markers, Annexin V, EpCAM, ASGR1 and CD133, could be used to identify tumour-associated EVs in circulation and distinguish between liver cancers (HCC and cholangiocarcinoma) and tumour-free cirrhosis." (PMID 35397694, 2022). "EpCAM+ cells were proposed as a tumour-initiating component in HCC development." (PMID 36612149, 2022). "Finally, the detailed mechanism related to tumor development and the potential biological function of EpCAM need to be further verified by systematic experimental studies." (PMID 35517503, 2022). "These were directed against tumor associated antigens such as human epidermal growth factor receptor (EGFR), epithelial cell adhesion molecule (EpCAM) and human epithelial growth factor receptor 2 (HER2), thereby retargeting Ovs to recognize a variety of tumor cell types." (PMID 35965554, 2022). "Whether the primary tumor–derived EpCAM+/ABCG2- CSCs exhibit BCG-induced PIBA requires further investigation." (PMID 36248858, 2022). "Moreover, anti-EpCAM mAbs are most widely used to collect circulating tumor cells (CTCs), which are useful indicators of micro-metastasis and provide important prognostic information to determine the response to therapeutic interventions." (PMID 35735360, 2022). "Moreover, we observed an increased number of Ki67+ EpCAM+ cells highlighting enhanced proliferation of tumor epithelial cells in cancer tissue of Stat3CCol1a2 mice as compared with littermate controls." (PMID 35326623, 2022). "Likewise, AAV- EpCAM targeted more than 90% of EpCAM-positive tumor cells in a mixture of cells, even when these cells were under-represented in the mixture." (PMID 35890005, 2022).
tumor (continued). "Similarly, CD133+EpCAM+ CSCs exhibited remarkable and greater tumor-initiating power compared to CD133+ cells." (PMID 36293184, 2022). "The proportion of EPCAM+ or GPC3+ cells was relatively stable in the tumor core regions while differences were noted when compared to the tumor border regions, suggesting that the proportion of those cells may vary among tumor regions." (PMID 36476645, 2022). "However, although anti-EpCAM IgG1 was highly effective in inducing EpCAM-specific tumor cell lysis, its potency was substantially lower compared with that of the EpCAM/CD16A and EpCAM/NKp46 ICE® constructs and anti-EpCAM Fc-enhanced IgG1." (PMID 35225870, 2022). "The organoids were composed of cells expressing epithelial markers such as EpCAM and E-cadherin and could show distinct tumor cell phenotypes." (PMID 35565191, 2022). "Furthermore, tumors are complex and are comprised of heterogeneous cell types, with CTCs that are defined by dual positivity for EpCAM and Cytokeratin only representing a fraction of the total tumor cells responsible for dissemination and relapse." (PMID 36167819, 2022). "Next, we employed lineage-specific markers to annotate clusters into major cell types of the tumor, including T cells (CD3G, CD4, CD8A, CD28, and IL7R), B cells (CD19 and CD20), myeloid cells (HLA-DRA and CD14), fibroblasts (THY1 and ACTA2), and tumor cells (EPCAM and S100A)." (PMID 35634306, 2022). "In addition to the EpCAM-labeled ferromagnetic beads used in the CellSearch system, AdnaTest includes a polymerase chain reaction (PCR) step to detect tumor-specific mRNA transcripts." (PMID 35303879, 2022). "Epithelial cell adhesion molecule (EpCAM) antibody-labeled magnetic beads were used to enrich tumor cells in CellSearch system, which defined the cells with cytomorphological tumor characteristics and phenylindole DAPI(+), cytokeratin CK(+), and leukocyte antigen CD45(-) as CTC." (PMID 35992876, 2022). "Circulating tumor-associated EVs were characterized according to CD133 and EPCAM expression." (PMID 35267665, 2022). "Similarly, in the CUHN013 tumor model, the expression of ephrinB2 appeared to be predominantly vascular, but moderate levels were also present on EpCam positive tumor epithelial cells." (PMID 35725568, 2022). "For instance, epithelial cell adhesion molecule (EpCAM) is an excellent target for tumor diagnostics and treatment because of its tumor-specific overexpression in cancer tissues, such as adenocarcinomas in the colon, stomach, pancreas, and epithelial breast cancer." (PMID 35877345, 2022). "Unexpectedly, EpCAM mAb at a dosage of 10 mg/kg resulted in considerable tumor elimination." (PMID 35281893, 2022). "The next generation of EpCAM-targeting antibodies is based on closing immune cells to tumor cells." (PMID 35986321, 2022). "Although the results obtained in flow cytometry agree with the biological decrease of EpCAM in advanced tumours, the objective of these experiments was to test whether this technique could be used to analyse EV proteins in non-processed plasma." (PMID 35135541, 2022). "EpCAM+ circulating tumour cells in breast cancer contain a subpopulation of metastatic cells." (PMID 35563449, 2022). "Supervised flow cytometry analyses showed that (i) most CD3+ TILs expressed PD-1 and TIGIT and, to a lesser extent, Tim-3, Lag3 and NKG2A, and (ii) EpCAM+ tumor cells and CD11b+ myeloid cells differed in their IC ligand expression profile, with a strikingly high expression of CD155 by tumor cells." (PMID 36077799, 2022). "Together, these data collectively support a model in which drug resistant colorectal CICs are confined to the small CD44v6 (+)/EpCAM (+)/ALDH1 (+)/CD133 (+) cell populations isolated from sphere-propagated tumor cells, which are enriched with FOLFOX therapy with high tumorigenic potential." (PMID 36330477, 2022).
tumor (continued). "Further measuring the markers related to the tumor formation ability in mice subcutaneous tumors, we found that EpCAM, CD13, CD24, CD44, CD90 and CD133 in ZNF334-OE cells was significantly lower than that of the control group, which was consistent to the phenotype of the mice model." (PMID 35534462, 2022). "Furthermore, most of our work has been performed in vitro, using hypoxia/oxidative stress–enhanced side-population cells or EPCAM+/ABCG2+ cells of established tumor cell lines." (PMID 36248858, 2022). "It is well established that EpCAM is an anchor molecule on circulating tumor cells (CTCs) which present the major source for metastatic cancer cells, and thus EpCAM may predict metastasis in some extent." (PMID 35517503, 2022). "Therefore, the fabricated VG-based electrochemical biosensor binds specifically to the EpCAM antigen via the anti-EpCAM antibody, which is the transmembrane glycoprotein found on tumor cells." (PMID 36296024, 2022). "Accordingly, inhibition of EpCAM could enhance the sensitivity of tumor cells to immune surveillance." (PMID 36369033, 2022). "Tumor cells were isolated based on low, moderate, and high EpCAM levels." (PMID 35216097, 2022). "A peripheral blood EpCAM+ circulating tumor cells (CTCs) is reported." (PMID 36293034, 2022). "CTCs are hypothesized to contain a significant number of EMT tumor cells, which are reported to have a low expression of epithelial surface antigens, especially EpCAM." (PMID 35962400, 2022). "A rich tumor stroma may promote the production of TGF-β, which directly upregulates the expression of tumor stem cell markers (EpCAM, K19, CD133, etc.), thereby promoting vascular invasion." (PMID 35349075, 2022). "Interestingly, CD24(+)CD44(+)EpCAM(+) CICs from the differentiated ductal-like cancer cells were found in the tumor mass." (PMID 35673567, 2022). "These platelets could shield tumor cell membrane proteins, including EpCAM, complicating CTC detection." (PMID 36613466, 2022). "Importantly, EpCAM is an excellent target for various therapeutic approaches, including immunotherapy, because it is uniformly expressed on the surface of tumor cells." (PMID 35911706, 2022). "Therefore, CAR-NK-based therapy has been performed on CRC, showing that EpCAM-CAR-NK-92 cells combined with Regorafenib suppress EpCAM-positive tumor xenografts." (PMID 36686835, 2022). "VSV-N could also be localized within the EpCAM+ve tumor cell compartment, demonstrating that tumor cells can be infected (n = 10/11)." (PMID 36097280, 2022). "Survival analysis suggests the negative impacts of bi-potent stem cells on patient outcomes, providing alternative clinical evidence for the tumour-initiating hypothesis of EpCAM+ cells." (PMID 36612149, 2022). "In tumor environment, cellular mechanisms may also be involved in CD45+EpCAM+ cell formation such as recently reported “ trogocytosis” when immune cells steal tumor cell membranes carrying surface protein." (PMID 35711455, 2022). "Additionally, induced EpCAM CAR NK cells derived from modified induced pluripotent stem cells displays anti-tumor activities as well, which provides a novel approach to generate CAR NK cells more efficiently." (PMID 36369033, 2022). "Therefore, intraperitoneal administration of catumaxomab offers the advantage of targeted, locoregional immunotherapy against EpCAM-positive tumor cells in the peritoneal cavity." (PMID 35740397, 2022). "In the control condition, anti-EpCAM CAR T cells efficiently lysed Panc02-EpCAM tumour cells." (PMID 36266575, 2022). "The remarkable antitumor response might be attributed to the targeting ability of EpCAM aptamer, which is present on the surface of NPs and helps the drug to accumulate at tumor site." (PMID 36686226, 2022).
tumor (continued). "Also, intravenous injection of EPCAM+Fat1-cKO tumor cells gave rise to a higher number of lung metastases as compared to tumor cells with wild-type FAT1, which clearly illustrated that deletion of FAT1 promotes metastasis in vivo." (PMID 35965328, 2022). "Overexpression of FTL, GPX4 and NUPR1 in UCA1+ EPCAM+ cells suggests these key genes may be upregulated further along the RMC oncogenic program to increase protection of the tumor against cell death induced by ferroptosis." (PMID 35837094, 2022). "However, EpCAM expression is not limited to tumor cells, as healthy epithelial cells express EpCAM as well." (PMID 36613466, 2022). "EpCAM is highly expressed on certain tumors and on tumor exosomes, which may induce cross-presentation of tumor-derived neoantigen (i.e., in exosomes or debris), resulting in better priming of tumor neoantigen-specific T cells." (PMID 35911742, 2022). "In addition, tumor-derived exosomes have also been identified to contain corresponding tumor biomarkers, such as EpCAM, PD-L1, and EGFR." (PMID 35281563, 2022). "In Huh-7 HCC cell lines, epithelial cell adhesion molecule (EpCAM)- and Prominin-1 (CD133)-co-expressing cell subpopulations were shown to possess stem cell-like properties, as they frequently caused tumor development in immunocompromised NOD/SCID mice xenograft models." (PMID 36556285, 2022). "Epigenetic alterations, like DNA methylation, in the promoter regions of tumor/metastasis suppressor genes, such as SOX17, BRMS1, and CST6 in EpCAM+ CTCs isolated from individuals with BC, are known to be correlated with enhanced tumor metastasis and poor prognosis." (PMID 35303879, 2022). "Finally, we addressed the proliferation of tumor epithelial cells by IF-staining for Ki67 and EpCAM." (PMID 35326623, 2022). "The anti-tumor activity of EpCAM-CAR-T cells against OC in vitro and in vivo indicated that the CAR-T might provide a promising therapeutic approach to OC." (PMID 35269636, 2022). "Here, we detected a reduced number of Ki67+ EpCAM+ cells in Stat3ΔCol1a2 mice as compared with littermate controls, indicating the reduced proliferation of tumor epithelial cells in mice with conditional STAT3 inactivation in type I collagen-expressing fibroblasts." (PMID 35326623, 2022). "Nevertheless, the finding of EpCAM-CD81-EVs in four initial stage patients, and not in advanced stage patients or healthy donors, agrees with previous observations that advanced tumour cells lose EpCAM expression as they undergo EMT (Epithelial to Mesenchymal Transition)." (PMID 35135541, 2022). "EpCAM-positive OC cells have greater tumor-initiating potential compared to EpCAM-negative cells." (PMID 35269636, 2022). "In summary, EpCAM + RB cells behave in vitro similarly to tumor stem cells." (PMID 36132125, 2022). "EpCAM aptamer-modified PEG-cationic liposomal NPs loaded with oncogenic miR-139-5p mimics exert anti-tumor effects through electrostatic adsorption of miR-139-5p mimics, long circulation time in vivo with the help of PEG and targeted binding of EpCAM to CRC cells." (PMID 35953863, 2022). "EpCAM is highly expressed in aggressive tumors compared to RB, a non-invasive tumor." (PMID 36132125, 2022). "Our results show that quercetin decreases the level of OV6 and EpCAM protein, indicating that quercetin may be inhibiting the tumor establishment as early as in the appearance of preneoplastic lesions." (PMID 35204240, 2022). "Moreover, Dong and coworkers prepared fluorescent magnetic mesoporous silica nanoparticles (M-MSNs) conjugated with fluorescein isothiocyanate (FITC) before modifying them with EpCAM antibody for efficient detection of circulating tumor cells (CTCs)." (PMID 35057223, 2022). "Tumor biomarkers (CK18/PD-L1/EpCAM/AFP) and endothelial cell biomarker CD31 are heterogeneously localized in the cytoplasm, on the nuclear envelope, or in the nuclei, while stem cell biomarker CD133 and mesenchymal cell biomarker Vimentin mainly showed an intracellular distribution." (PMID 35311070, 2022).
tumor (continued). "In K14-creER; KRasG12D; Tp53f/f mice, the mesenchymal marker Vimentin of IFE stem cell-derived highly differentiated SCCs was restricted to the tumor mesenchymal region, and the expression of epidermal markers, epithelial cell adhesion molecule (Epcam) and E-cadherin, increased." (PMID 35784923, 2022). "Moreover, logistic analysis demonstrated a positive significant correlation between age, tumor stage, and tumor differentiation and higher expression of EpCAM." (PMID 35016698, 2022). "Thus, such tumor cells that lose EpCAM expression are less likely to be detected by assays utilizing cell immunological characteristics." (PMID 35962400, 2022). "EpCAM was found to be related to DNA methylation and tumor-infiltrating immune cells." (PMID 35517503, 2022). "Furthermore, there seemed to be a correlation between the potency of anti-EpCAM IgG1 and EpCAM expression levels on the cell surface of tumor cells." (PMID 35225870, 2022). "PRC2-repressed genes, such as EpCAM and pluripotency genes (Nanog, Sox2 and Oct4), which are commonly expressed in progenitor hepatic cancer cells, are also upregulated through this mechanism, and are indicative of poor prognosis following tumor resection." (PMID 35154157, 2022). "The surface display of EpCAM- or HER2-binding proteins enabled selective targeting of the cells overexpressing tumor antigens, while the attachment of the IL-8- or IL-6-binding proteins to the L. lactis surface provided the bacteria with cytokine removal capacity." (PMID 35155394, 2022). "CellSearch enriches for circulating tumor cells (CTCs) using the cell surface marker Epithelial Cell Adhesion Molecule (EpCAM), which makes it unable to detect cells with downregulated EpCAM undergoing epithelial-to-mesenchymal transition (EMT) and mesenchymal CTCs." (PMID 36167819, 2022). "Combined staining of EpCAM and EGFR as tumor–associated markers might explain the high sensitivity of our ISX protocol." (PMID 35681790, 2022). "A common way to kill EpCAM+ tumor cells is to use immunotoxins." (PMID 35986321, 2022). "Besides, because of the plasma membrane proteins on the surface including galectin-3, N-cadherin, and epithelial cell adhesion molecule, tumor-derived micro-vesicles possess some unique properties such as antigenic display and homologous binding." (PMID 35477389, 2022). "Generally, immuno‐based microfluidic and microarray technologies have utilised tetraspanins (CD9, CD81 and CD63) and tumour‐cell surface associated markers such as EpCAM, CA125, CD19, EGFR, EGFRvIII, podoplanin and PDGFR for on‐chip capture of tumour‐EV sub‐populations." (PMID 36239734, 2022). "This was approximately 10-fold lower than EpCAM expression on primary and metastatic tumor tissue." (PMID 36613466, 2022). "The EpCAM+ tumor epithelial cells may, to some extent, compensate for the lack of human APC functions in the PDX model by expressing human leukocyte antigen (HLA)-ABC and HLA-DR." (PMID 35740548, 2022). "Anti-EpCAM magnetic particles conjugate to tumor cells and be immobilized by a magnetic force." (PMID 35856010, 2022). "We further evaluated the mRNA expression of EpCAM in multiple tumor tissues." (PMID 35517503, 2022). "They isolated tumor cells based on their surface marker expression levels on the anti-EpCAM antibody-coated chip and anti-HER2 antibody-coated chip and achieved capture efficiencies of 98.91% for EpCAM+ cells and 86.51% for HER2+ cells, respectively, with 22% purity, at high throughput (24 mL/h)." (PMID 35216097, 2022). "Blocks simultaneously CD44 and EpCAM, reducing tumor progression and promoting apoptosis." (PMID 35785191, 2022). "EPCAM was identified as a pivotal factor in regulating tumor immune phenotypes." (PMID 35150083, 2022).